RN7SL539P (RNA, 7SL, cytoplasmic 539, pseudogene)
Gene: Miscellaneous RNA gene on chromosome 15 (32,446,674 to 32,446,964, reverse strand). Ensembl gene ENSG00000274076.
Homologues: Orthologues: pig Metazoa_SRP (52% identical). Paralogues in human: RN7SL196P (100% identical), RN7SL286P (100% identical), RN7SL796P (99% identical), Metazoa_SRP (88% identical), RN7SL106P (88% identical), RN7SL238P (88% identical), RN7SL545P (88% identical), RN7SL759P (88% identical), RN7SL536P (88% identical), RN7SL185P (80% identical), RN7SL628P (80% identical), RN7SL82P (80% identical), and 701 more.